SALL4 (spalt like transcription factor 4)
Diseases named in the same sentence as SALL4 in open-access papers (continued):
Sharing a sentence is not in itself a finding about the gene and the disease.
clear cell carcinoma (3 papers, 2012 to 2025). "It has been shown that SALL4 is only weakly positive in three out of 45 clear cell carcinomas in ovaries." (PMID 22848863, 2012). "SALL4 is a highly sensitive and specific marker for OGCT and is particularly useful in differentiating yolk sac tumors from clear cell carcinoma, where other markers, such as AFP or glypican-3, show lower sensitivity and specificity." (PMID 41373846, 2025).
colon adenocarcinoma (3 papers, 2022 to 2026). "SALL4 induces the invasion and metastasis of colon adenocarcinoma (COAD) and is significantly correlated with TNM grading, histological grading, and lymphatic metastasis in tumor tissues." (PMID 38584262, 2024). "CAED is a rare subtype of colonic adenocarcinoma characterized by increased AFP production and expression of at least one enteroblastic marker, including AFP, glypican 3, or SALL4." (PMID 41589237, 2026). "The development and progression of many cancers may be related to SALL4, the role and molecular mechanism of which are unclear in colon adenocarcinoma (COAD)." (PMID 35692499, 2022).
lung adenocarcinoma (3 papers, 2021 to 2024). A carcinoma that arises from the lung and is characterized by the presence of malignant glandular epithelial cells. "We performed immunohistochemistry to examine the expression of aldehyde dehydrogenase 1 (ALDH1) and Sal-like 4 (SALL4) in 46 cell block samples of MPE from patients with lung adenocarcinoma." (PMID 34441397, 2021). "SALL4 upregulation has also been reported, and SALL4 mRNA expression is considered a drug resistance factor in lung adenocarcinoma." (PMID 34441397, 2021). "To investigate the expression of ALDH1 and SALL4 in MPE from patients with lung adenocarcinoma, we performed IHC using SALL4 and ALDH1 antibodies and patient-derived MPE cell blocks." (PMID 34441397, 2021). "A subpopulation with positive ALDH1 and/or SALL4 expression in lung adenocarcinoma MPE could influence tumorigenicity and proliferation, and it might be associated with poor prognosis." (PMID 34441397, 2021). "Therefore, the SALL4-positive cell subpopulation in lung adenocarcinoma MPE influences cancer cell proliferation." (PMID 34441397, 2021). "We demonstrated the expression patterns of ALDH1 and SALL4 in MPE of lung adenocarcinoma." (PMID 34441397, 2021).
pancreatic cancer (3 papers, 2022 to 2024). "A recent study has identified the SALL4high PDAC subset that is associated with the poor prognosis, indicating SALL4 as a potential biomarker in pancreatic cancer." (PMID 38584262, 2024). "The SALL4‐related stromal network might also be of interest in discriminating stromal components associated with pre‐invasive and invasive pancreatic carcinomas." (PMID 36587397, 2023). "Transduction of SALL4 confers to MRC5 the ability to promote colony formation of pancreatic cancer cells (BPC8) and Colo320 cell line." (PMID 36587397, 2023). "Our findings identify the transcription factor SALL4 as a new biomarker in pancreatic cancer (PDAC)‐derived stroma." (PMID 36587397, 2023). "The function and regulation of SALL4 in pancreatic cancer have received less attention." (PMID 38584262, 2024). "However, whether SALL4 acts via this pathway in pancreatic cancer is still unclear and worth investigating." (PMID 38584262, 2024).
renal agenesis (3 papers, 2024 to 2025). Renal agenesis (RA) is a form of renal tract malformation characterized by the complete absence of development of one or both kidneys (unilateral RA or bilateral RA respectively), accompanied by absent ureter(s). "This study elucidates the molecular mechanism by which SALL4 mutations cause renal agenesis and provides new targets for the treatment and intervention of this disease." (PMID 40483479, 2025). "Previous studies have found that heterozygous variants in SALL4 are associated with CAKUT or renal agenesis, with reported variants including p.Arg329His, p.Ser579Arg, p.Arg831Gln, p.Val837Gly, and p.Lys1049Arg." (PMID 40483479, 2025). "In summary, this study identified a SALL4 mutation that leads to renal agenesis and investigated the molecular mechanisms underlying its pathogenicity." (PMID 40483479, 2025). "We performed whole-exome sequencing (WES) to identify pathogenic variants in a fetus with unilateral renal agenesis and confirmed a variant in SALL4 using Sanger sequencing." (PMID 40483479, 2025). "This mutation is associated with unilateral renal agenesis and duplication of renal pelvis, providing valuable insights for genetic counseling and prenatal diagnosis of SALL4-related disorders." (PMID 40809379, 2025). "A novel truncating mutation in SALL4 was identified through WES in a fetus with unilateral renal agenesis." (PMID 40483479, 2025). "These genes were mainly enriched in the fetal kidney ureteric bud cells, indicating that renal agenesis caused by SALL4 variant may be related to developmental abnormalities during the fetal kidney ureteric bud cell period." (PMID 40483479, 2025). "This study elucidated the molecular mechanism by which SALL4 mutations lead to renal agenesis." (PMID 40483479, 2025). "Additionally, we found that these differentially expressed genes mainly regulated fetal ureteric bud cells, suggesting that SALL4 mutations may ultimately lead to unilateral renal agenesis by affecting the development and function of fetal ureteric bud cells." (PMID 40483479, 2025). "Therefore, the SALL4 mutant protein may cause renal agenesis by failing to transcriptionally activate WNT11 and PAX2, thus affecting kidney development." (PMID 40483479, 2025). "In addition, studies have reported that mutations in the SALL4 gene can lead to non-DRRS-related diseases, such as premature ovarian insufficiency and kidney abnormalities, including renal agenesis." (PMID 40483479, 2025).
sarcoma (3 papers, 2023 to 2024). A usually aggressive malignant neoplasm of the soft tissue or bone. "Moreover, immunohistochemistry was positive for stemness marker SALL4, which is typically associated with loss of H3K27me3 in DICER1 sarcomas." (PMID 38178234, 2024).
ameloblastoma (2 papers, 2022 to 2023). The most common odontogenic tumor, arising from the epithelial component of the embryonic tooth and usually affecting the molar-ramus region of the mandible or maxilla. "Chi-square test was used to compare the frequency of distribution of categorized total IRS score with fascin and SALL4 in various odontogenic tumors (Ameloblastoma and its histopathological variants, AOT) and odontogenic cysts (OKC, DC, COC, RC)." (PMID 38895097, 2022). "Semi-quantitative analysis of fascin and SALL4 immuno-positive cells was done in a total of 40 cases of ameloblastoma (11 plexiform, 12 follicular, 12 unicystic, and 5 desmoplastic) variants, 6 cases of AOT, 15 each of OKC, DC, RC and 5 of COC." (PMID 38895097, 2022). "A moderate to weak immune-reactivity to SALL4 was observed in the cytoplasm of ameloblastoma, epithelial cells of dentigerous and radicular cysts, having a marked inflammatory infiltrate, which was an interesting observation." (PMID 38895097, 2022). "In various histopathological grades of ameloblastoma, SALL4 was expressed in the majority of cases." (PMID 38895097, 2022). "In this study, the expression of SALL4 and fascin were evaluated in ameloblastoma, adenomatoid odontogenic tumor (AOT), odontogenic keratocyst (OKC), dentigerous cyst (DC), radicular cyst (RC), and calcifying odontogenic cyst (COC)." (PMID 38895097, 2022).
cholangiocarcinoma (2 papers, 2023 to 2025). A carcinoma that arises from the intrahepatic biliary tree (intrahepatic cholangiocarcinoma) or from the junction, or adjacent to the junction, of the right and left hepatic ducts (hilar cholangiocarcinoma). "Furthermore, correlation analysis using cholangiocarcinoma datasets from The Cancer Genome Atlas (TCGA-CHOL) showed that WNT pathway genes (AXIN2, CTNNB1, LEF1) positively correlated with TIC signature genes (KIT, SALL4, CD44, SOX2)." (PMID 39774471, 2025). "In a cohort of combined HCC and cholangiocarcinoma, GPC3 immunopositivity rates were much higher in SALL4-positive samples than that of SALL4-negative samples." (PMID 38173713, 2023).
chordoma (2 papers, 2024). Chordomas are rare malignant tumors arising from embryonic remnants of the notochord in axial skeleton. "In our case, complete loss of INI1, with EMA negative, SMA negative, GFAP negative, chromogranin negative and sal-like protein 4 (SALL-4) positive guided our diagnosis towards ATRT rather than dedifferentiated/poorly differentiated chordoma." (PMID 39634169, 2024).
craniofacial microsomia (2 papers, 2018 to 2025). "In addition, in zebrafish models, Tet2/3 and Sall4 regulate pharyngeal cartilage development via a TET-BMP-Sall4 axis, critical for craniofacial microsomia pathogenesis." (PMID 40442783, 2025).
deafness (2 papers, 2017 to 2023). An inherited or acquired condition characterized by the complete loss of the ability to hear from one or both ears. "We identified five predicted highly suspected deafness-associated genes, namely, COL1A1, GJC3, RRM2B, SALL4 and SALL1, in the available databases, including Ensemble and OMIM, indicating that they were correctly identified as deafness-associated genes." (PMID 36803022, 2023).
epithelioid sarcoma (2 papers, 2024). An aggressive malignant neoplasm of uncertain differentiation, characterized by the presence of epithelioid cells forming nodular patterns. "However, epithelioid sarcoma is SMARCB1-deficient with retained SMARCA2 expression, and the expression of SOX2 and SALL4 is deficient." (PMID 38347129, 2024). "The loss of SMARCA4 (BRG-1) can exceptionally occur in tumors such as SMARCB1/INI1-retained epithelioid sarcoma (ES); in this context, the absence of SOX2 and SALL4 expression aids in distinguishing ES from SMARCA4-UT." (PMID 38265099, 2024).
Infertility (2 papers, 2018 to 2022). "Deletion of Sall4 in the primary follicle stage or primordial follicle stage oocytes causes oocyte immaturity and infertility, demonstrating the requirement for Sall4 in female germ cells." (PMID 30401915, 2018).
liver cirrhosis (2 papers, 2014 to 2018). "Additionally, enzyme-linked immunosorbent assay (ELISA) was used to measure the SALL4 levels in serum samples isolated from patients as follows: 127 with HCC, 27 with HBV, 24 with liver cirrhosis, and 23 normal controls." (PMID 24860834, 2014). "We further detected the serological levels of SALL4 from 127 patients with HCC, 27 patients with chronic hepatitis, 24 patients with liver cirrhosis, and 23 normal controls." (PMID 24860834, 2014).
malignant rhabdoid tumor (2 papers, 2012 to 2025). "Rhabdoid tumors have also been shown to have an SE resident at an overlapping position upstream of the SALL4 gene and similarly depend upon its expression for rhabdoid tumor cell line growth." (PMID 39906560, 2025).
metastatic carcinoma (2 papers, 2020 to 2023). A carcinoma which has spread from the original site of growth to another anatomic site. "Human SALL4 has been reported to be significantly elevated in metastatic cancer cells." (PMID 32098783, 2020).
metastatic disease (2 papers, 2013 to 2025). "We have shown SALL4 may be a new molecular marker of metastatic tumor." (PMID 23363002, 2013). "It is suggested that SALL4 not only might be important in pathogenesis of GCTs, especially to maintain their poorly differentiated status, but also can be used as a highly specific marker to confirm the germ cell origin of a metastatic tumor, due to its sensitivity and specificity." (PMID 23363002, 2013). "GATA3, TTF-1, S100, p40, PAX8, p63, NKX3.1, CDX2, SALL4, CD30 (-) were detected to rule out metastatic disease." (PMID 40978995, 2025).
oral cancer (2 papers, 2023 to 2024). "Inhibitors targeting pathways regulating OCSC properties, such as the METTL3/SALL4 axis, which activates the Wnt/β-catenin pathway post-radiation therapy, are being tested in preclinical trials and offer promising avenues for potentially curative oral cancer therapies." (PMID 39200273, 2024). "The METTL3/SALL4 axis, which activates the Wnt/β-catenin pathway post-radiation therapy, enhances the CSC phenotype and leads to radio-resistance in oral cancer, representing a potential therapeutic target to eliminate radio-resistant oral cancer cells." (PMID 39200273, 2024).
oral squamous cell carcinoma (2 papers, 2023 to 2024). "In addition, CD44, a tumor stem cell marker for oral squamous cell carcinoma, showed high expression in radioresistant cells, indicating the possibility that SALL4 is associated with radioresistance in CD44( + )-OSCC cells." (PMID 38355684, 2024).
osteosarcoma (2 papers, 2022). A usually aggressive malignant bone-forming mesenchymal neoplasm, predominantly affecting adolescents and young adults. "MiR-107 inhibited osteosarcoma cell proliferation via targeting SALL4." (PMID 36545680, 2022).
acute B-cell lymphoblastic leukemia (1 paper, 2024). "The activity of caspase-3/8 in SALL4 knockout cells is elevated in acute B-cell lymphoblastic leukemia, indicating that SALL4 maintains the survival of tumor cells by inhibiting caspase family members." (PMID 38584262, 2024).
acute leukemia (1 paper, 2013). A clonal (malignant) hematopoietic disorder with an acute onset, affecting the bone marrow and the peripheral blood. "SALL4 is highly expressed and plays an important role in embryonic stem cells, primitive germ cells, HSCs/HPCs and acute leukemia." (PMID 24283261, 2013).
acute promyelocytic leukemia (1 paper, 2013). An aggressive form of acute myeloid leukemia (AML), characterized by arrest of leukocyte differentiation at the promyelocyte stage, due to a specific chromosomal translocation t(15;17) in myeloid cells. "It has been reported that SALL4 functions as a regulator of cell survival in human acute promyelocytic leukemia cells by targeting and regulating a wide range of genes in both pro-apoptotic and anti-apoptotic pathways." (PMID 23363002, 2013).
bladder tumors (1 paper, 2020). "TFCP2L1‐positive cells in bladder tumors displayed high expression levels of SALL4 and CD44 CSC markers." (PMID 31709755, 2020).
cholestasis (1 paper, 2025). Impairment of the bile flow caused by obstruction within the liver, or outside the liver in the bile duct system. "Beyond its role in tumorigenesis, we examined the role of SALL4 in regenerative HC reprogramming using a DDC-fed cholestasis model." (PMID 40932240, 2025). "Additionally, in the DDC–fed cholestasis model, Sall4 deletion enhanced HC-to-LPC activation while impairing LPC differentiation into mature CCs." (PMID 40932240, 2025). "Our study identifies SALL4 as a crucial regulator in YAP1-mediated HC-to-CCA malignant transformation and regenerative HC-to-CC conversion in a cholestasis model." (PMID 40932240, 2025).
colorectal tumor (1 paper, 2013). "SALL4 is a zinc finger transcriptional activator crucial for maintenance of self-renewal in stem cells; however, its expression level has not yet been elucidated in colorectal tumor cells." (PMID 23363002, 2013).
Congenital fibrosis of the extraocular muscles type 1 (1 paper, 2017). "Congenital fibrosis of the extraocular muscles type 1 (CFEOM1) is known to be caused by mutations in KIF21A or TUBB3 or other known genes (SALL4, CHN1, HOXA1)." (PMID 29110737, 2017).
congenital heart disease (1 paper, 2018). A heart disease that is present at birth. "Strikingly, heterozygous loss of function mutations in SALL4 result in a human developmental condition that phenocopies thalidomide-induced birth defects such as absence of thumbs, phocomelia, defects in ear and eye development, and congenital heart disease." (PMID 30067223, 2018).
cystic kidneys (1 paper, 2009). "We observed that 50% of examined SALL4B transgenic mice had cystic kidneys, which suggested that SALL4 could be involved in kidney development." (PMID 19440552, 2009). "The SALL4-mediated repression of the expression of PTEN and SALL1 has been confirmed both in vitro and in vivo and is associated with phenotypes observed in SALL4B transgenic mice, i.e. AML and cystic kidneys, respectively." (PMID 19440552, 2009).
diabetes mellitus (1 paper, 2014). A metabolic disorder characterized by abnormally high blood sugar levels due to diminished production of insulin or insulin resistance/desensitization. "Younger age and lower frequency of diabetes mellitus in patients with SALL4-positive HCC may be associated with the higher prevalence of an HBV-positive background, since HBV-positive patients in this study showed these trends (data not shown)." (PMID 26034695, 2014).
embryonal rhabdomyosarcoma (1 paper, 2024). A poorly circumscribed morphologic variant of rhabdomyosarcoma. "An expression of SALL4 was occasionally detected in mesenchymal and neuroectodermal neoplasm, and only in one case of embryonal rhabdomyosarcoma (1/43, 2%)." (PMID 39001344, 2024).
endometrioid adenocarcinoma (1 paper, 2025). An adenocarcinoma characterized by the presence of malignant glandular epithelial cells resembling endometrial cells. "A diagnosis of high-grade endometrioid adenocarcinoma with YST differentiation was rendered based on the morphologic features and immunopositivity for SALL-4, glypican-3, and AFP." (PMID 41510478, 2025).
endometriosis (1 paper, 2022). The growth of functional endometrial tissue in anatomic sites outside the uterine body. "There was also no significant change in the level of SALL-4 (1.751187 fold, P ≤ 0.06) gene expression in endometriosis cells." (PMID 35059465, 2022).
endothelial dysfunction (1 paper, 2023). In vascular diseases, endothelial dysfunction is a systemic pathological state of the endothelium (the inner lining of blood vessels) and can be broadly defined as an imbalance between vasodilating and vasoconstricting substances produced by (or acting on) the endothelium. "The “anti‐endothelial dysfunction (anti‐ED)” list consists of 31 genes that significantly ameliorate the ED phenotypes, with JUNB, NR4A3, SALL4, CSF2 and HEY1 being the top hits." (PMID 38031960, 2023).
Fanconi anemia (1 paper, 2018). Fanconi anemia (FA) is a hereditary DNA repair disorder characterized by progressive pancytopenia with bone marrow failure, variable congenital malformations and predisposition to develop hematological or solid tumors. "There is also evidence that SALL4-Fanconi anemia complementation group L interactions exist." (PMID 29651423, 2018). "This loop explains the overlapping phenotypes of four syndromes: Duane-radial ray syndrome with SALL4 mutations (MIM 607323); Fanconi anemia (MIM 227650); Holt-Oram syndrome with TBX5 mutations (MIM142900); and Townes-Brocks syndrome with SALL1 mutations (MIM 107480)." (PMID 29651423, 2018).
granulosa cell tumours (1 paper, 2015). "Sex cord-stromal tumours including adult granulosa cell tumours are, however, negative for PLAP, OCT4 and SALL4." (PMID 26742984, 2015).
hearing loss (1 paper, 2023). "Site-specific mutations in COL1A1, GJC3, RRM2B, SALL4, and SALL1 cause otosclerosis ([MIM:120150]), delayed hearing sensitivity ([MIM:611925]), sensorineural deafness ([MIM: 604712]), hearing loss ([MIM:607343]) and ear dysplasia ([MIM:602218]), among other deafness-related disorders." (PMID 36803022, 2023).
heart-hand syndrome (1 paper, 2021). Heart-hand syndrome refers to a group of congenital disorders characterized by malformations of the upper limbs and heart. "Given that the patient's clinical diagnosis was heart-hand syndrome, we screened the TBX5, SALL4, and LMNA genes, but no deleterious variation was found." (PMID 34485408, 2021).
Hepatomegaly (1 paper, 2019). Abnormally increased size of the liver. "Where, the SALL4 gene expression tends to be lower in most cases of splenomegaly and hepatomegaly." (PMID 31653163, 2019).